MICB (MHC class I polypeptide-related sequence B)
Diseases named in the same sentence as MICB in open-access papers (continued):
Sharing a sentence is not in itself a finding about the gene and the disease.
breast carcinoma (20 papers, 2014 to 2025). "Because only 12 breast cancer patients had elevated MICB serum levels above the ELISA detection limit, further correlation between MICB and the clinical parameters was not performed." (PMID 38612935, 2024). "We also observed that breast cancer cells expressed a high level of MICA/MICB, which was a kind of ligands of NKG2D." (PMID 35894707, 2022). "Resveratrol upregulates MICA and MICB through suppressing the c-Myc/miR-17 pathway in breast cancer cells, and it has been shown to increase the cytolysis of breast cancer cells via NK cells." (PMID 35566016, 2022). "Resveratrol treatment increased the surface levels of MICA and MICB on breast cancer cells in a dose-dependent manner." (PMID 29029468, 2017). "Here, we report that resveratrol upregulated the protein and mRNA expression of MICA and MICB in breast cancer cells, which in turn promoted breast cancer cell lysis by natural killer (NK) cells in vitro and in vivo." (PMID 29029468, 2017). "Functional analyses in this study demonstrated that resveratrol increased the susceptibility of breast cancer cells to lysis by NK cells in vitro and in vivo by inducing MICA and MICB expression." (PMID 29029468, 2017). "In conclusion, resveratrol elevated MICA and MICB expression in breast cancer cells by suppressing the c-Myc/miR-17 pathway, thus increasing the susceptibility of breast cancer cells to lysis by NK cells." (PMID 29029468, 2017). "Resveratrol thus upregulates MICA and MICB by suppressing the c-Myc/miR-17 pathway in breast cancer cells, and increases the cytolysis of breast cancer cells by NK cells." (PMID 29029468, 2017). "MiR-17 expression correlated inversely with MICA and MICB expression and overall survival in two sets of breast cancer specimens." (PMID 29029468, 2017). "MICA and MICB expression increased or decreased in breast cancer cells transfected with a miR-17 inhibitor or mimic, respectively." (PMID 29029468, 2017). "This notwithstanding, downregulation of MICA/MICB has been observed in stem-like breast cancer cells, due to the altered expression of the oncogenic microRNA miR20a." (PMID 28404796, 2017). "The same mechanism has been demonstrated for miR-10b/MICB pair in murine breast cancer model, and for miR-20a, miR-93, miR-106b/MICB pair in hepatocellular cell lines." (PMID 27349385, 2016). "miR-10b in breast cancer EVs directly targets and downregulates stress-induced cell surface molecules, including MICB (MHC class I polypeptide-related sequence B), a critical ligand for NKG2D receptors on natural killer (NK) cells, which are crucial for recognizing and cytotoxic elimination." (PMID 41463227, 2025). "Resveratrol upregulates protein and mRNA expression of major histocompatibility complex class I chain-related proteins A and B (MICA and MICB) in breast cancer cells, which in turn promote breast cancer cell lysis by natural killer (NK) cells in vitro and in vivo." (PMID 34572548, 2021). "Resveratrol has also been reported to elevate the major histocompatibility complex class I chain-related proteins A and B (MICA and MICB) expression in breast cancer cells by suppressing the c-Myc/miR-17 pathway, thus enhancing the susceptibility of breast cancer cells toward NK cells." (PMID 33802331, 2021). "MICA and MICB expression are regulated by different miRNAs, namely miR-20a, miR-93, miR-520d, miR-106b, and miR-373, with oncogenic functions in several human cancer cells, including prostate, kidney and breast cancer cell lines." (PMID 32316552, 2020). "To determine whether resveratrol could increase the expression of MICA and MICB in breast cancer cells, we exposed BCap37, MDA-MB-231, Hs 578T and MCF-7 cells to 6.25 μM or 25 μM resveratrol for 48 h." (PMID 29029468, 2017).
breast carcinoma (continued). "It binds multiple ligands, including MHC class I chain-related A (MICA), MICB and several UL-16 binding proteins (ULBPs), which are induced after cellular stress and are the most common ligands for NK cell receptors in breast carcinomas together with DNAM-1 ligands." (PMID 26595802, 2016). "In addition, MICA and MICB can also be induced by a variety of cell signaling pathways in different cell types; for example, HER2/HER3 signaling regulates the expression of MICA and MICB in human breast cancer cells." (PMID 24885711, 2014). "sMICB levels appeared to be rather low in breast cancer patients, which could either indicate that the cleavage of MICB is less relevant in breast cancer or that the breast tumors of the analyzed patients did not initially express membrane-bound MICB at relevant levels." (PMID 38612935, 2024). "Similarly, it has been recently found that increased expression of MICB could be considered a good prognostic factor for OS for patients with breast cancer." (PMID 32316552, 2020). "Therefore, resveratrol treatment could be a feasible way to improve the MICA and MICB mediated anticancer effects in breast cancer patients." (PMID 29029468, 2017). "Furthermore, ADAM17 in MDA-MB-231 breast cancer cells cleaves MICA/MICB from the cell surface of the cancer cell to produce a soluble form, sMICA/sMICB, which may result in a type of immune decoy." (PMID 26601108, 2015). "A flow cytometric analysis was conducted to assess the expression of NKG2DLs, including hULBP-1, hULBP-2-5-6, hULBP-3, MICA, and MICB, in three tumor cell lines: A549 (lung adenocarcinoma), HELA (cervical cancer), and MCF-7 (breast cancer)." (PMID 40076725, 2025). "To evaluate the expression of NKG2DL in primary breast cancer material (n = 200), we used the TCGA database analysis and observed predominant expression of MICA, MICB and ULBP2." (PMID 37685962, 2023). "In our analysis of 56 clinical breast cancer specimens and data from TCGA, it was obvious that miR-17 expression correlated inversely with MICA and MICB expression, potentially indicating that miR-17 inhibited MICA/B expression." (PMID 29029468, 2017). "Hence, this enhanced killing of the breast cancer cells can clearly be attributed to the recognition of NKG2D ligands such as MICA and MICB on the target cells’ surface by the NKG2D-based NKAR receptor." (PMID 38334638, 2024). "Resveratrol suppresses the c-Myc/miR-17 pathway in breast cancer cells to upregulate major histocompatibility complex class I chain-related proteins A and B (MICA and MICB) that promote antitumor immune responses by increasing cytolysis of breast cancer cells by natural killer (NK) cells." (PMID 36439106, 2022). "Exosomes from T47D breast carcinoma cells decreased the amount of NKG2D-positive lymphocytes within peripheral blood lymphocytes (PBL), which was modulated through NKG2D ligands such as MICB, CD81, and MHC Class I on exosomes." (PMID 26601108, 2015). "Thus, high expression of miR-17, which showed a negative correlation with MICA and MICB levels, might predict a poor prognosis in breast cancer patients." (PMID 29029468, 2017).
viral infection (19 papers, 2010 to 2024). "MICB is upregulated upon stress exposure such as viral infections, DNA damage, and malignant transformation." (PMID 38539461, 2024). "Malignant transformation or viral infection of the cells induce surface NKG2D ligands (MICA and MICB) expression that makes cancer cells susceptible to immune destruction." (PMID 37761005, 2023). "The miR-UL112-3p binding site partially overlaps that of a cellular miRNA, theoretically impeding host regulation of the MICB transcript during viral infection while ensuring that the miRNA target site within the MICB 3’ UTR is maintained." (PMID 30360396, 2018). "The peak of viral infections is between the first and third week, which coincides with maximal serum MICB and ULBP1 concentrations, and with NKG2D downregulation." (PMID 26745675, 2016). "On the one hand, the expression of MICB andother stress induced ligands of NKG2D must be rapidly induced after insults such as viral infection or transformation." (PMID 25426550, 2014). "The production of MICA and MICB by virus-infection or tumor cells has been previously reported, and the ability of these ligands to induce cytotoxic activity in NK cells and other cytotoxic lymphocytes through the interaction with their cognate receptor, NKG2D, has been well established." (PMID 21477352, 2011). "Many studies suggest that this miRNA might be involved in regulating both host and viral gene expression during viral infection to establish and maintain latency through targeting genes, such as MICB, immediate-early (IE) gene products, Toll-Like Receptor (TLR), and Interleukin-32 (IL-32)." (PMID 36591247, 2022). "Thus, these cells could be a key for a rapid defense against bacterial and viral infections and contribute to control viral load through a higher MICB expression (from the exposed seronegative individuals), activating an effective natural response via NKG2D." (PMID 34650566, 2021). "VmiR-UL112 specifically binds to MICB-3′ untranslated regions (3′UTR) and downregulates MICB expression during viral infection, therefore, leading to decreased binding of NKG2D and reduced killing by NK cells." (PMID 28484438, 2017). "Since both viral infection and malignant transformation induce expression of the immune activating NKG2D ligands MICA and MICB, we screened for the respective mRNA expression among 75 MCC tumors from 61 patients and a number of MCC cell lines." (PMID 26902929, 2016). "The MICB is a known ligand for natural killer cell activating receptor NKG2D, which is over-expressed on cell surfaces after stress such as that induced by viral infection and cell transformation." (PMID 21203544, 2010). "MICB and IFN-y are both critical in the immune response, and thus variations within these genes could have strong effects on the initial response to the viral infection and the subsequent disease pathogenesis." (PMID 29929468, 2018). "Expression of the stress-induced ligands MICA, MICB and ULBP 1–6 are up-regulated as a cellular response to DNA damage, excessive proliferation or viral infection; thereby, they enable recognition and annihilation by immune cells that express the powerful activating receptor NKG2D." (PMID 26982091, 2016). "Therefore, due to viral infections and long-term inflammation, MIC proteins (MICA and MICB) can be over-expressed." (PMID 25626490, 2015). "In conclusion, our results suggest that MIC levels in the airways are increased in response to virus infection in healthy subjects, but not subjects with asthma, and airway MICB levels correlated with NK cells at the peak of the RV infection." (PMID 24556715, 2014). "HCMV-miR-UL112 specifically binds to MICB-3′ untranslated regions (3′UTR) and inhibits MICB translation, and non-miR-UL112 viral infection leads to an increase in MICB at the cell surface and easier recognition and destruction by NK cells." (PMID 27077876, 2016).
acute myeloid leukemia (11 papers, 2014 to 2025). Acute myeloid leukemia (AML) is a group of neoplasms arising from precursor cells committed to the myeloid cell-line differentiation. "In patients with chronic lymphocytic leukemia (CLL), acute myeloid leukemia (AML), and multiple myeloma, NK cells show reduced expression of NKG2D, which in turn is linked to enhanced levels of MICA and MICB, thereby causing anergy in NK cells." (PMID 38239881, 2023). "In the presented study, we investigated the single amino acid changes across the exons 2–4 of MICA and MICB genes, and point mutations within the NKG2D gene, which defines the type of NKG2D haploblock (HNK/LNK) in the donors (n = 124), as well as in patients with acute myeloid leukemia (n = 78)." (PMID 34682758, 2021). "Shedding of NKG2D ligands, including MICA, MICB and ULBP2, is inhibited by TIMP-3 in acute myeloid leukemia (AML) cells, and this process enhances their sensitivity to lytic activity of NK." (PMID 35207132, 2022).
colorectal cancer (9 papers, 2020 to 2025). A primary or metastatic malignant neoplasm that affects the colon or rectum. "In other cancers, such as colorectal cancer, an association between MICB expression and a favorable prognosis has been documented." (PMID 39596210, 2024). "MICB expression has been reported to increase in response to oxidative stress and its overexpression may be associated with favorable prognosis in colorectal cancer." (PMID 40863222, 2025). "MiR-17-5p has been documented to suppress the expression of MICA and MICB, two other important NKG2DLs, in hepatocellular and colorectal cancers." (PMID 39963142, 2025). "MICA and MICB are also expressed on the surface of colorectal cancer cells derived from intestinal epithelium cells." (PMID 40563539, 2025). "Among these sixteen genes, MICB have been reported as a biomarker for good prognosis in colorectal cancer." (PMID 36843983, 2023). "In this study, a large cohort of real world was constructed as primary cohort to evaluate the prognostic benefit of MICB in colorectal cancer patients." (PMID 32306128, 2020). "In this study, we explored the prognostic effect of MICB in colorectal cancer." (PMID 32306128, 2020). "Malignant tumors derived from the digestive system, such as gastric cancer, colorectal cancer, and liver cancer, all have high levels of MICA or MICB expression, as well as high levels of MMPs or ADAMs." (PMID 40563539, 2025). "A study using human colorectal carcinoma cell lines demonstrated that MICA and MICB mRNA and surface protein expression were low when cells were at high confluency and quiescent." (PMID 33352921, 2020). "Moreover, it was reported that IGF2BP3 could facilitate tumor immune escape by down-regulating the stress-induced ligands MICB and ULPB2 in colorectal carcinoma." (PMID 34446007, 2021). "In a similar study performed on the human colorectal carcinoma cell line CaCo-2, oxidative stress induced by H2O2 also increased MICA and MICB mRNA expression, although surface protein levels were not measured." (PMID 33352921, 2020).
hepatocellular carcinoma (9 papers, 2013 to 2026). A malignant tumor that arises from hepatocytes. "NKG2D ligands, including MICA, MICB, and ULBPs, can be widely expressed in hepatoma cells." (PMID 32075046, 2020). "MS-275 modified hepatoma cell-derived ExVs carrying increased levels of HSP70 and MICB could significantly increase the cytotoxicity of NK cells and proliferation of PBMCs." (PMID 33435564, 2021).
lung carcinoma (9 papers, 2019 to 2026). "Epidermal growth factor receptor (EGF-R), CD20 and MICA and MICB were expressed on the surface of A549 lung cancer cells and Raji B-cell lymphoma cells." (PMID 35967081, 2021). "Because of its role in antigen binding and natural killer cell lectin-like receptor binding, MICB had been found to be related in several types of cancers, involving lung cancer cell lines and leukemia." (PMID 30926680, 2019). "Treating NCI-H23 and A549 lung cancer cells with FK228 led to an increase in the transcription of the five NKG2D ligands: MICA, MICB, ULBP1, ULBP2, and ULBP3." (PMID 34203519, 2021). "The transcription of NKG2D ligands, namely, MHC class I polypeptide-related chain proteins A (MICA), MICB, UL16 binding protein 1 (ULBP1), ULBP2, and ULBP3, was analyzed after treating lung cancer cells with five types of HDAC inhibitor for 18 h." (PMID 34203519, 2021). "The lung cancer cell line A549 highly expressed MICA, MICB, ULBP1, and ULBP2/5/6." (PMID 35965586, 2022).
glioma (8 papers, 2014 to 2023). A benign or malignant brain and spinal cord tumor that arises from glial cells (astrocytes, oligodendrocytes, ependymal cells). "Treatment of glioma cells with the catalytic LSD1 inhibitors tranylcypromine (TCP) or GSK LSD1 was able to increase MICB and ULBP4 expression, enhancing human NK-cell mediated lysis of the target cells." (PMID 37090711, 2023). "The fold changes of the MICB (p = 0.038) and MIF (p = 0.012) genes were observed to be lower in the glioma group relative to the control group." (PMID 34643804, 2022). "First, we monitored by flow cytometry the cell surface expression of the NKG2D ligand MICA, MICB, ULBP1, ULBP2, ULBP3, ULBP4 and MHC class I on untreated and SR141716-treated U251 glioma cells at 24 h to exclude that the possibility of observed effects are linked to the stress of dying cells." (PMID 26008966, 2015). "Previous studies and our data demonstrated that most gliomas expressed MICA and ULBP proteins, but not MICB." (PMID 31288857, 2019).
multiple myeloma (8 papers, 2015 to 2024). "MICB is internalized and retained intracellularly in several tumor cell lines, while in Multiple Myeloma (MM) cells the constitutive internalization of MICB is followed by its lysosomal degradation." (PMID 31736972, 2019). "Other groups demonstrated that high concentrations of the Hsp90 inhibitor 17-AAG (1 and 6 μM) up-regulate the cell surface density of MICA and MICB on multiple myeloma cells and Hodgkin’s lymphoma cells and thereby can enhance NK cell cytotoxicity." (PMID 25854583, 2015). "In addition to the increase in CD38 levels, we have demonstrated that tinostamustine augments the expression of several NKG2D ligands, especially MICA and MICB, in myeloma cell lines, an event that may also be beneficial when combining tinostamustine with immunotherapy treatments." (PMID 38731936, 2024). "We analyzed the morphology of the patient primary myeloma cells for expression levels of MHC I, MICA, MICB, ULBP1, ULBP2/5/6, HLA-E, CD38 (n = 12), CD112, CD155, ICAM-1 and PD-L1 (n =5) using flow cytometry." (PMID 35413499, 2022). "Also, the expression of MICA and MICB, ligands for the NK cell activating receptor NKG2D, augments after tinostamustine treatment in myeloma cell lines and primary myeloma cells." (PMID 38731936, 2024). "In multiple myeloma cells, LXRs activation enhanced the NK cell-cytotoxicity activity by upregulating the NKG2D ligands, namely, MHC class I polypeptide-related sequence-A (MICA) and MICB respectively." (PMID 38550382, 2024). "The multiple myeloma cell line IM9 highly expressed MICA, MICB, and ULBP4." (PMID 35965586, 2022). "In multiple myeloma cells, the LXRs activation by GW3965 hydrochloride and LXR-623 agonists enhanced the NK cell-cytotoxicity activity by upregulating the NKG2D ligands such as MHC class I polypeptide-related sequence-A (MICA) and MHC class I polypeptide-related sequence-B (MICB) respectively." (PMID 38550382, 2024). "In fact our results indicate that ex vivo exposure of primary myeloma cells to tinostamustine does not generally augment the levels of CD38 but is able to increase the expression of MICA and MICB." (PMID 38731936, 2024).
schizophrenia (8 papers, 2017 to 2025). A major psychotic disorder characterized by abnormalities in the perception or expression of reality. "These included microtubule-related MAP2 and MAPT, as well as WNT3 and MICB, all implicated in the pathogenesis of diseases such as Parkinson’s, Alzheimer’s and schizophrenia." (PMID 31504236, 2019). "MICB (rs6916394) a previously noted Caucasian candidate, was associated with schizophrenia at the p = 0.02 level." (PMID 28855605, 2017). "Another gene in the MIC family is MICB, which is also associated with schizophrenia risk." (PMID 36196481, 2022). "Of note, rs3094128 is an eQTL of MICB, which is crucial to brain development and plasticity and may mediate both genetic and environmental involvements in schizophrenia." (PMID 31504236, 2019). "MICB was found differentially expressed between schizophrenia cases and controls." (PMID 30705251, 2019).